PTH (parathyroid hormone)
Diseases named in the same sentence as PTH in open-access papers (continued):
Sharing a sentence is not in itself a finding about the gene and the disease.
hypoparathyroidism (continued). "Management of hypoparathyroidism is based on substitution with calcium and an active form of vitamin D. Another possibility is the use of recombinant human parathormone rh-PTH 1-84 once daily." (PMID 38116790, 2023). "In the present study, the sensitivity of a low level of PTH in predicting medical treatment for hypoparathyroidism was moderate (just below 70 per cent), albeit with a high sensitivity (almost 90 per cent)." (PMID 37758507, 2023). "A logistic regression model for quotient variables showed, at the limit of statistical significance, a relationship between the incidence of hypoparathyroidism and preoperative PTH levels." (PMID 37626794, 2023). "TransCon PTH treatment was well‐tolerated, normalized mean 24‐hour urine calcium excretion, and led to improvements in HRQoL and hypoparathyroidism‐related symptoms, functioning, and well‐being." (PMID 36271471, 2023). "The sensitivity and specificity for a low PTH value to predict permanent hypoparathyroidism was 100 and 73.6 per cent respectively." (PMID 37758507, 2023). "Two of these had a low level of PTH on the first day after surgery, and two were treated temporarily for postoperative hypoparathyroidism." (PMID 37758507, 2023). "TransCon parathyroid hormone (PTH), which uses a similar approach to maintain physiological PTH concentrations in patients with hypoparathyroidism, recently met its primary endpoint in a Phase 3 clinical trial." (PMID 36839922, 2023). "Post-operatively, lab tests showed a nadir PTH of 561 pmol/L and nadir serum-corrected calcium level of 1.75 mmol/L, suggesting post-surgical hypoparathyroidism." (PMID 36334246, 2023). "The disease‐specific HPES showed improvements in hypoparathyroidism‐related symptoms, functioning, and well‐being for participants treated with TransCon PTH." (PMID 36271471, 2023). "Hypoparathyroidism (low calcium and low PTH) represents a more frequent complication/outcome after PTx and it is the main differential diagnostic of HBS." (PMID 37296804, 2023). "PTH <1.2 pg/ml within three days after surgery was predictive in patients with permanent hypoparathyroidism." (PMID 37545843, 2023). "Hypoparathyroidism is the most frequent complication after bilateral thyroid surgical interventions and consists in decreasing both parathyroid hormone (PTH) and calcium serum levels, below the lower reference value." (PMID 37198359, 2023). "In view of the lower mean adjusted serum calcium level in the fracture group, we suggest regular monitoring of calcium, vitamin D and PTH levels to ensure adequacy of calcium and vitamin D supplementation and timely treatment of hypoparathyroidism." (PMID 35490138, 2022). "The end of the operation until 24 h after surgery are the best time points to measure PTH levels to predict postsurgical hypoparathyroidism." (PMID 36050906, 2022). "Postsurgical measurements of PTH levels are more sensitive and more specific than intraoperative PTH measurements to predict postsurgical hypoparathyroidism." (PMID 36050906, 2022). "In our study, the one patient (100%) in the experimental group who developed permanent hypoparathyroidism eventually recovered normal PTH secretion 12 months after surgery." (PMID 35992841, 2022). "Hypoparathyroidism is defined as low calcium levels in presence of inappropriately normal or low parathyroid hormone (PTH) levels." (PMID 35389883, 2022). "PTH levels below 15 and 10 pg/ml have a high sensitivity and specificity to predict the development of postsurgical hypoparathyroidism reliably." (PMID 36050906, 2022). "A few mutations have been described in patients, associated with abnormal processing of prepro-PTH, or affecting the mature PTH protein, resulting in hypoparathyroidism." (PMID 36246903, 2022). "Normal PTH levels have been recorded on the first postoperative day, which indicates a 100% of positive predictive value for excluding postoperative hypoparathyroidism." (PMID 36561508, 2022).
hypoparathyroidism (continued). "The guidelines of the European Society of Endocrinology and the ATA define permanent hypoparathyroidism as a low PTH concentration 6 months after surgery." (PMID 35992841, 2022). "Our study used low blood calcium (more objective) and lower PTH levels to determine hypoparathyroidism." (PMID 36644104, 2022). "Postsurgical hypoparathyroidism is generally defined as chronic (permanent) when PTH secretion is insufficient to maintain normocalcemia 6-12 months after surgery." (PMID 35250859, 2022). "Hypoparathyroidism is an endocrine disorder that occurs because of the inability to produce parathyroid hormone (PTH) effectively." (PMID 35203648, 2022). "Bone disease occurs in hypoparathyroidism due to the absence or low levels of PTH and so markedly reduced bone remodeling." (PMID 35250859, 2022). "As for the long-term PTH levels, 3 of 172 (1.74%) patients exhibited permanent hypoparathyroidism: two from the combined group and one from the calcium group." (PMID 36091150, 2022). "A new approach to the treatment of hypoparathyroidism is the use of PTH analogs limitations imposed by the high cost." (PMID 36382754, 2022). "Parathyroid hormone (PTH) and electrolyte tests confirmed hypoparathyroidism; calcium gluconate injection 2 g Bid was given intravenously during the following stay, and calcium carbonate 0.6 g Bid was given after discharge." (PMID 36031657, 2022). "The single permanent hypoparathyroidism patient recovered normalized PTH secretion 12 months after surgery." (PMID 35992841, 2022). "Hypoparathyroidism is an endocrine disorder that occurs because of the inability to produce parathyroid hormone (PTH) effectively and is the most common result of damaged or removed of parathyroid glands during thyroidectomy." (PMID 35203648, 2022). "An endocrine disorder called hypoparathyroidism is recognized by a decrease in the amount of PTH, an 84-amino acid long polypeptide." (PMID 36381723, 2022). "Our meta‐analysis of the largest available number of treated patients demonstrates that PTH replacement therapy is well‐tolerated, safe, and effective in the management of hypoparathyroidism." (PMID 35485213, 2022). "In our study, hypoparathyroidism was defined as PTH <15 pg/ml, and venous blood was collected on postoperative day 1 to measure PTH levels." (PMID 35311081, 2022). "Of note, inflammatory cytokines, including IL-6, have been described to increase the parathyroid calcium-sensing receptor (CaSR), which reduces parathyroid hormone (PTH) secretion, resulting in inflammation-associated hypocalcemic hypoparathyroidism." (PMID 36233666, 2022). "Several previous studies and our long-term clinical practice have found that most patients have transient hypoparathyroidism; that is, plasma PTH levels can be recovered within six months." (PMID 35937810, 2022). "After the surgery, serum parathyroid hormone and calcium levels decreased, and hypoparathyroidism was corrected with calcium carbonate and calcitriol." (PMID 36583007, 2022). "The prevalence of hypoparathyroidism as a post-operative complication was found to be more among patients who had two and three PTH gland dissections (33.3% and 25.5% respectively)(p=0.045)." (PMID 36644104, 2022). "On the other hand, the reduction of PTH levels is a good predictor for symptomatic hypoparathyroidism." (PMID 36050906, 2022). "The preoperative PTH was significantly lower in the hypoparathyroidism group (42.94 vs. 48.5, p < 0.001)." (PMID 34956363, 2021). "This study also analysed day 1 postoperative PTH levels, which are a useful marker of postoperative hypoparathyroidism." (PMID 33498810, 2021). "Especially, due to the very short half-life of PTH (3–5 mins), early postoperative PTH determination can help to detect postoperative hypoparathyroidism." (PMID 35071309, 2021). "An independent relationship between day 1 postoperative PTH level and the incidence of permanent hypoparathyroidism was explored with a Fisher’s exact test." (PMID 33498810, 2021).
hypoparathyroidism (continued). "A blunted PTH response (functional hypoparathyroidism) was prevalent among 19.7% (n = 62) of the women studied, while 80.3% (n = 253) exhibited an elevated PTH response." (PMID 34580590, 2021). "A recent phase two trial on TransCon PTH has shown promising results regarding phosphate control in adult hypoparathyroidism." (PMID 34884774, 2021). "Day 1 PTH status is a reliable predictor of postoperative hypoparathyroidism with a sensitivity of 83.4% and a specificity of 100%." (PMID 33498810, 2021). "Long-term hypoparathyroidism occurred in 21 cases (3.9%), of which 19 cases had parathyroid hormone lower than normal, and two cases had normal parathyroid hormone but required calcium supplementation to maintain normal blood calcium." (PMID 34095206, 2021). "This study used blood calcium (more objective) and PTH laboratory test indicators to determine hypoparathyroidism." (PMID 34095206, 2021). "After reoperation, one patient presented with transient vocal cord paresis (4%) and early postoperative hypoparathyroidism (PTH <3 pg/ml) was found in 5 patients (20.8%)." (PMID 34552559, 2021). "The utility of day 1 PTH in predicting transient hypoparathyroidism is well documented, although its role in permanent hypoparathyroidism is lesser known." (PMID 33498810, 2021). "PTH on the first day after surgery has a predictive effect on patients with long-term hypoparathyroidism." (PMID 34095206, 2021). "The European Society of Endocrinology Clinical Guideline also used 6-month duration to diagnose long-term hypoparathyroidism; however, their definition includes a low PTH level." (PMID 32700234, 2021). "Our data revealed that immediate hypoparathyroidism on postoperative day one still occurred in three patients with at least one well-perfused parathyroid gland, but their PTH levels all normalized in one week." (PMID 34575620, 2021). "Given its role in the regulation of calcium and PTH levels, vitamin D was presumed as a potential predictor of postoperative hypoparathyroidism." (PMID 34956363, 2021). "In a subgroup analysis, the study examines the predictive utility of day 1 parathyroid hormone (PTH) in permanent hypoparathyroidism." (PMID 33498810, 2021). "Postoperative transient hypoparathyroidism occurred in 194 cases (36.1%), among which 135 cases (25.1%) had parathyroid hormone lower than normal, and 156 cases (29.1%) had blood calcium lower than normal." (PMID 34095206, 2021). "This was explored in this cohort for both the incidence of day 1 hypoparathyroidism between study groups and the presence of an independent effect between low postoperative PTH and permanent hypoparathyroidism." (PMID 33498810, 2021). "Hypoparathyroidism is a rare endocrine disorder resulting from undetectable or inappropriately low circulating levels of parathyroid hormone (PTH), which is the principal regulator of calcium and phosphate homeostasis." (PMID 34801015, 2021). "The European Guidelines defined permanent hypoparathyroidism as low serum parathyroid hormone (PTH) levels and/or need for replacement therapy after six months after surgery, and the American Thyroid Association chose six months as the cut-off time as well." (PMID 33953701, 2021). "PTH treatment, by increasing renal calcium reabsorption, would be expected to decrease urinary calcium excretion in hypoparathyroidism." (PMID 32765831, 2020). "As long‐acting PTH (LA‐PTH) ligands hold interest as potential treatments for hypoparathyroidism (HP), we explored the structural basis in the ligand for stable R0 binding and prolonged cAMP signaling." (PMID 32666018, 2020). "Compared with group A, serum intact PTH (P < 0.001) and total calcium levels (P < 0.05) in group B significantly improved on the first postoperative day, and the incidence of transient hypoparathyroidism significantly dropped in group B (P < 0.001)." (PMID 32404116, 2020).
hypoparathyroidism (continued). "Future clinical trials should be conducted on patients with hypoparathyroidism after PTH treatment to investigate the FGF23 functions more accurately." (PMID 33198660, 2020). "Hypoparathyroidism is an endocrine disorder characterized with lower levels or dysfunction of parathormone (PTH)." (PMID 32267362, 2020). "Hypoparathyroidism-related hyperphosphatemia refers to the low levels of PTH, which typically promotes phosphate excretion." (PMID 33015068, 2020). "The duration for defining permanent hypoparathyroidism ranges from 3 to 12 months postsurgery, the PTH levels range from 8.0 pg/ml to 15.0 pg/ml, and serum Ca levels range from 1.9 mmol/L to 2.10 mmol/L." (PMID 32802056, 2020). "Variables including serum intact parathyroid hormone (PTH), total calcium, the incidence of transient, and permanent hypoparathyroidism were studied." (PMID 32404116, 2020). "The aim of this study was to evaluate the association of ferritin, intact PTH, FGF23, and l,25(OH)2D3 in patients with major thalassemia having normal parathyroid function and hypoparathyroidism." (PMID 33198660, 2020). "Transient hypoparathyroidism has been described as low PTH level immediately after surgery before beginning any supplementation." (PMID 32555278, 2020). "Although most patients with a low postoperative PTH recover parathyroid function quickly, approximately 4% of them develop a permanent hypoparathyroidism that persists beyond 6 months after surgery." (PMID 33967947, 2020). "The mean serum calcium and PTH levels were lower in patients with hypoparathyroidism (8.7 ± 1.6 mg/dL, and 13.93 ± 4.6 pg/mL) than the control (10.1 ± 0.9 mg/dL, and 55.6 ± 15.7 pg/mL), (P = 0.001 and P < 0.001, respectively)." (PMID 33198660, 2020). "Hypoparathyroidism is an abnormal condition characterized by low levels of parathyroid hormone (PTH)." (PMID 33967947, 2020). "Serum PTH, calcium and corrected serum calcium levels were significantly lower whereas phosphorus and CaXP product value were significantly higher in the hypoparathyroidism group when compared to the control group." (PMID 32267362, 2020). "The current treatment for postoperative hypoparathyroidism has shortcomings, such as repeated blood monitoring for dosage adjustment, uncertain long-term efficacy, and the high price of recombinant parathyroid hormone therapy." (PMID 32612651, 2020). "Hypoparathyroidism is genetically heterogeneous and characterized by low plasma calcium and parathyroid hormone (PTH) concentrations." (PMID 31961795, 2020). "Pseudohypoparathyroidism differs biochemically from hypoparathyroidism by the occurrence of detectable and often elevated serum PTH levels." (PMID 32751307, 2020). "TransCon PTH is a sustained‐release, essentially inactive prodrug transiently bound to an inert carrier, designed to release PTH(1‐34), and in development for hypoparathyroidism (HP)." (PMID 32212275, 2020). "The mean serum calcium and parathyroid hormone level was significantly lower in hypoparathyroid patients in comparison with the control group (P < 0.001 and P < 0.001, respectively)." (PMID 32398014, 2020). "Hypoparathyroidism is an endocrine disease characterized by low serum calcium levels due to insufficient parathyroid hormone (PTH) secretion mostly resulting from damage to or removal of the parathyroid glands during thyroid or neck surgery." (PMID 31956849, 2020). "Pathogenic mutations in the parathyroid hormone gene (PTH) and glial cells missing transcription factor 2 (GCM2) have been associated with both autosomal dominant and recessive hypoparathyroidism." (PMID 32986719, 2020). "Continuous subcutaneous infusion of PTH(1‐34) with an insulin pump to hypoparathyroid patients mimicked endogenous PTH secretion more closely than intermittent PTH injections." (PMID 32765831, 2020). "Accidentally removed parathyroid glands are still challenging in neck surgery, leading to hypoparathyroidism characterized with abnormally low levels of parathyroid hormone." (PMID 32456711, 2020).
hypoparathyroidism (continued). "Lower PTH levels within normal limits accompanied by hypocalcemia are classical for hypoparathyroidism." (PMID 32267362, 2020). "Surgery for thyroid, throat, and other head-neck tumors, as well as parathyroidectomy in patients with parathyroid hyperplasia, usually leads to hypoparathyroidism characterized with abnormally low levels of parathyroid hormone (PTH)." (PMID 32456711, 2020). "Then, we will establish an animal model of hypoparathyroidism and autotransplant the differentiated ADSCs into the rats and measure blood calcium and PTH in tail vein blood of rats to evaluate the therapeutic effect of autologous transplantation." (PMID 32612651, 2020). "We searched PubMed, MEDLINE, EMBASE and Cochrane databases from January 2000 to March 2018 using keywords ‘hypoparathyroidism, diagnosis, treatment, calcium, PTH, calcidiol, calcitriol, hydrochlorothiazide and pregnancy’." (PMID 30540559, 2019). "The biochemical profile is the same as seen in hypoparathyroidism with low serum calcium and high phosphate; however, PTH levels are elevated." (PMID 30540559, 2019). "Activating antibodies to the calcium-sensing receptor can suppress PTH secretion leading to hypoparathyroidism." (PMID 30540559, 2019). "The diagnosis of hypoparathyroidism is made in the presence of low serum calcium (ionized or adjusted for albumin) and low or inappropriately normal PTH confirmed on two separate occasions." (PMID 30540559, 2019). "The pivotal trials for both obeticholic acid (Ocaliva) for primary biliary cirrhosis and parathyroid hormone (Natpar) for hypoparathyroidism reported biomarker endpoints." (PMID 31504034, 2019). "PTH resistance syndromes have the same biochemical profile as hypoparathyroidism however PTH levels are elevated." (PMID 30540559, 2019). "Subjects with hypoparathyroidism, typically with very low or undetectable PTH levels, have high serum phosphorus and FGF23, consistently with PTH requirements for a full phosphaturic FGF23 effect." (PMID 30736285, 2019). "Most guidelines on thalassemia managment recommend screening for hypoparathyroidism at 16 years by assessing Ca & P; followed by PTH if low Ca or P is found." (PMID 31360455, 2019). "On the other hand, secondary forms, also identified as Fahr’s syndrome, have been associated with different conditions: endocrine abnormalities of PTH, such as hypoparathyroidism, other genetically determined conditions, brain infections, or toxic exposure." (PMID 31267306, 2019). "In patients who developed hypoparathyroidism, PTH levels decreased more rapidly when compared with the decline in serum calcium level." (PMID 30989072, 2019). "As expected, the serum levels of calcium, phosphate, and PTH differed significantly between the groups, with patients with hypoparathyroidism presenting lower calcium and higher phosphate levels when compared with those in the control group." (PMID 29791658, 2018). "Hypoparathyroidism (HypoPT) is characterized by low levels of plasma calcium with inappropriately low levels of parathyroid hormone, as well as high phosphate levels." (PMID 29971010, 2018). "A total of 2077 records showed PTH or Ca or both under the 5th centile of distribution, possibly representing samples from patients with hypoparathyroidism." (PMID 30283895, 2018). "Traditional treatment of hypoparathyroidism is unable to prevent these manifestations (B), and results obtained with PTH replacement show discrepancies between studies (B)." (PMID 29694629, 2018). "This nicotine-induced hypoparathyroidism is supported by studies reporting reduced serum 1,25-dihydroxyvitamin D concentration, along with subnormal parathyroid hormone concentration, and elevated serum phosphorus in smokers." (PMID 30296288, 2018). "One would expect to see elevated serum P levels in these hypoparathyroid patients because of impairment of both phosphaturic hormones, PTH and FGF-23." (PMID 29726397, 2018).